SYNJ1 (synaptojanin 1)
Diseases named in the same sentence as SYNJ1 in open-access papers (continued):
Sharing a sentence is not in itself a finding about the gene and the disease.
Alzheimer disease (15 papers, 2009 to 2025). A progressive, neurodegenerative disease characterized by loss of function and death of nerve cells in several areas of the brain leading to loss of cognitive function such as memory and language. "Previous studies suggest that SYNJ1 polymorphisms have significant impact on the age of onset of Alzheimer’s disease (AD) and that SYNJ1 is involved in amyloid-induced toxicity." (PMID 32493451, 2020). "Elevated levels of Synj1 are also found in individuals showing a high risk for the development of Alzheimer's disease (AD)." (PMID 33349335, 2020). "SYNJ1 downregulation in Alzheimer's disease models is protective towards amyloid-beta peptide (Aβ) toxicity." (PMID 25302295, 2014). "Thus genes such as RUNX1 (which may contribute to childhood leukaemia in people with DS), APP (a key Alzheimer disease gene) and SYNJ1, RCAN1 and ITSN1, which have been linked to endosomal/synaptic abnormalities are unlikely to contribute to the phenotype of this mouse model of DS." (PMID 23596509, 2013). "Synaptojanin 1 was found upregulated in synaptosome preparations of the Ts65Dn partial trisomic mouse model of DS and its genetic ablation successfully attenuates neurodegeneration in an Alzheimer’s disease mouse model, accelerating beta-amyloid clearance." (PMID 31803016, 2019). "Indeed, it has been suggested that synaptojanin-1 is involved in the cognitive defects observed in Down syndrome, and that PIP2 metabolism may be linked to synaptic dysfunctions in Alzheimer disease." (PMID 19402746, 2009).
cognitive deficits (11 papers, 2009 to 2025). "Surprisingly, increased endosome enlargement and ApoE4-linked cognitive impairments in AD are correlated with higher levels of SYNJ1, and ApoE4-associated cognitive deficits in AD." (PMID 36552875, 2022). "Increased level of insoluble SYNJ1 in AD brains may induce toxicity and could be associated with synaptic dysfunction and eventually with cognitive deficits as previously reported." (PMID 32493451, 2020). "Also, it has been observed that SYNJ1 mutations induce severe dyskinesia with generalized seizures in childhood, dystonia, developmental delay, cognitive impairment, and oculomotor disturbances even when coupled with low-dose levodopa therapy." (PMID 29163333, 2017). "Down-regulating the expression of synaptojanin 1 in mice through transgenic method reduces cognitive deficits of mice." (PMID 29208987, 2017). "However, we report here a male patient heterozygous for a novel frameshift mutation in SYNJ1 who displays a late-onset, slowly progressive form of typical PD and responds well to low-dose levodopa therapy without apparent cognitive impairment." (PMID 29163333, 2017).
Down syndrome (11 papers, 2009 to 2024). "Some of the polymorphisms in SYNJ1 are also linked with age of onset in familial AD, late-onset AD and Down syndrome with AD." (PMID 33716646, 2021). "SYNJ1, whose gene is located in chromosome 21, is linked to endolysosomal abnormalities in Down syndrome." (PMID 33716646, 2021). "Mutation at trisomy 21q22.11 consisting of SYNJ1 found in patients with Down syndrome, the disorder is indicated with enlarged endosomes due to overexpression of SYNJ1." (PMID 33627135, 2021). "SYNJ1 expression is exacerbated in old individuals with Down syndrome with AD-like neuropathological lesions (DSAD)." (PMID 32493451, 2020). "Several studies have shown that lipid phosphatase Synaptojanin1 (SYNJ1) is profoundly involved in human neurodegenerative diseases such as AD, early onset Parkinson’s disease (PD) and Down syndrome (DS)." (PMID 32493451, 2020). "Triplication of SYNJ1 in Down's syndrome is responsible for higher level of phosphoinositides, enlarged endosomes, and learning deficits." (PMID 25302295, 2014). "In addition, in mouse models of Down syndrome, SYNJ1 overexpression contributed to enlarged EE and brain dysfunction." (PMID 31413155, 2019). "Dysregulation of endocytosis in Down syndrome has been linked to an increased dose of several endosomal pathway-related genes that map to chromosome 21, such as amyloid precursor protein (APP), synaptojanin-1 (SYNJ1), intersectin-1 (ITSN1), and regulator of calcineurin 1 (RCAN1)." (PMID 38540156, 2024). "Patients with Down syndrome have the tendency to show early onset of Alzheimer’s disease, which indicate the overexpression of APP and SYNJ1 and subsequent decrease in PI 4,5-P2 levels." (PMID 33627135, 2021).
epilepsy (7 papers, 2020 to 2024). A brain disorder characterized by episodes of abnormally increased neuronal discharge resulting in transient episodes of sensory or motor neurological dysfunction, or psychic dysfunction. "Whereas excessive Synj1 expression leads to memory deficits in rodent, homozygous Synj1 knockout mice are lethal and a rare human homozygous nonsense mutation in SYNJ1 caused epilepsy and severe tau pathology in a young child." (PMID 32493451, 2020). "Interestingly, most of the pathological SYNJ1 mutations are located in one of the two phosphatase domains, although recently, a new pathological SYNJ1 mutation was reported in the C-terminal domain of the longer isoform in a Tunisian family with juvenile Parkinson’s disease associated with epilepsy." (PMID 34299248, 2021). "Mutations in STRADA, SYNJ1, CACNA1A and NPRL3 have also been reported with severe epilepsy-related disease, but the association has not been reported for heterozygous variants in isolated forms of epilepsy." (PMID 36539902, 2022).
developmental delay (4 papers, 2017 to 2025). "SYNJ1 mutations can also cause seizures and developmental delay, particularly with homozygous p.R136X mutations that produce a near-complete loss of function." (PMID 41179085, 2025). "Collectively, mutations in DNAJC6, SYNJ1, and RAB39B highlight the particular vulnerability of synaptic vesicle trafficking pathways, showing how disruptions first manifest as developmental delay or juvenile parkinsonism but may later converge on mechanisms central to late-onset neurodegeneration." (PMID 41179085, 2025).
Dystonia (4 papers, 2017 to 2022). An abnormally increased muscular tone that causes fixed abnormal postures. "SYNJ1 is known to be a causative gene for early-onset Parkinsonism, with atypical characteristics, such as seizures, dystonia, and dementia, with an autosomal-recessive inheritance pattern." (PMID 33117265, 2020).
tauopathies (4 papers, 2017 to 2021). "The parkinsonian patients with SYNJ1 mutation showed clinical and radiological signs reminiscent ofother tauopathies, such as vertical gaze palsy and atrophy of the quadrigeminalplate, suggesting that a tauopathy might be the underlying cause." (PMID 28733970, 2017).
brain injury (2 papers, 2020 to 2021). Acute and chronic (see also brain INJURIES, CHRONIC) injuries to the brain, including the cerebral hemispheres, CEREBELLUM, and brain STEM. "Reduction of SYNJ1 has been proposed as a therapeutic target for amyloid-induced toxicity, amyloid clearance and tau pathology after traumatic brain injury." (PMID 32493451, 2020). "Furthermore, miR-148a-3p acted as a apoptosis enhcaner via the activation of the SYNJ1/PI3K/Akt signaling pathway, highlighting a potential therapeutic target in the treatment of infants with hyperthermia-induced brain injury." (PMID 33441699, 2021).
cognitive decline (2 papers, 2021). "Moreover, the reduction of Synj1 accelerated the clearance of the toxic Aβ peptide and consequently attenuated cognitive decline." (PMID 34572436, 2021).
dementia (2 papers, 2020 to 2021). Loss of intellectual abilities interfering with an individual's social and occupational functions. "One key protein linking phosphoinositol metabolism with several dementias is synaptojanin 1 (SYNJ1)." (PMID 33841102, 2021).
Epileptic encephalopathy (2 papers, 2023 to 2025). A condition in which epileptiform abnormalities are believed to contribute to the progressive disturbance in cerebral function. "Autosomal recessive mutations lead to early‐onset atypical parkinsonism with uncharacterized neuropathology or epileptic encephalopathy with neuronal tau pathology indicating loss of SYNJ1 function is associated with Tau neuronal pathology and development of atypical parkinsonism." (PMID 36847488, 2023).
Intellectual disability (2 papers, 2019 to 2022). "Taken together, these findings provide evidence that Synj1 might contribute to intellectual disability in individuals with DS." (PMID 35646085, 2022).
neuroblastoma (2 papers, 2018 to 2022). Neuroblastoma (NB) is the most common solid, extracranial childhood tumor. "To this aim, we stably transfected human neuroblastoma derived SH-SY5Y cells with a plasmid vector encoding Synj1." (PMID 35646085, 2022). "To analyse the role of loss of Synj1 function on endosomal trafficking, we produced two human cell lines, HeLa and neuroblastoma-derived SH-SY5Y cells, in which the expression of Synj1 was interfered by plasmid vectors encoding specific short hairpin RNAs (shRNAs; see Materials and methods section)." (PMID 29515184, 2018).
oculocerebrorenal syndrome (2 papers, 2015 to 2023). Oculocerebrorenal syndrome of Lowe (OCRL) is a multisystem disorder characterized by congenital cataracts, glaucoma, intellectual disabilities, postnatal growth retardation and renal tubular dysfunction with chronic renal failure. "Specifically, we selected synaptojanin 1⁄2 (SYNJ1/2), INPP5E, INPP5J, oculocerebrorenal syndrome of Lowe (OCRL), INPP5B, and INPP5K, of which INPP5E/B and OCRL have already been shown to alter ciliary lipid composition." (PMID 38110903, 2023).
Spastic paraplegia (2 papers, 2016 to 2023). Complete loss of the ability to move the lower limbs accompanied by spasticity of the lower limbs. "Therefore, we suggest that the genetic interaction and protein haploinsufficiency of SPG11 and SYNJ1, both proteins implicated in common biochemical pathways, cause clinical spastic paraplegia of late onset." (PMID 37510225, 2023). "In conclusion, we report for the first time a known heterozygous recessive SPG11 c.1951C>T mutation and a not-reported heterozygous recessive SYNJ1 c.2614G>T mutation in a European Caucasian patient with clinical spastic paraplegia of late onset." (PMID 37510225, 2023). "No cases of spastic paraplegia have been reported to be caused by monoallelic recessive SPG-11 or SYNJ1 mutations." (PMID 37510225, 2023).
amyloid (1 paper, 2020). "Taken together, these data suggest that SYNJ1 is clearly associated with Alzheimer lesions such as NFTs, Hirano bodies and Synaptophysin-positive dystrophic neurites surrounding amyloid plaques." (PMID 32493451, 2020). "A SYNJ1 immunoreactivity was detected as globular structures around amyloid plaques in AD brains." (PMID 32493451, 2020).
bipolar disorder (1 paper, 2014). A disorder of the brain that causes unusual shifts in mood, energy, activity levels and the ability to carry out day-to-day tasks. "Several studies have linked bipolar disorder (BPD) to chromosomal region 21q22 containing SYNJ1 in a subset of families." (PMID 25302295, 2014).
convulsion (1 paper, 2021). A rapid and repeated body muscle contract that results in an uncontrolled shaking of the body. "Through comprehensive analysis, we found that miR-148a-3p may affect the occurrence and development of convulsions through its potential target gene, SYNJ1." (PMID 33441699, 2021).
DOORS syndrome (1 paper, 2020). DOORS syndrome (also known as DOOR syndrome) is a multiple congenital anomalies-intellectual disability syndrome characterized by sensorineural hearing loss (deafness), onychodystrophy, osteodystrophy, mild to profound intellectual disability, and seizures. "Finally, these observations also have implications for the window that is available to therapeutically target the 5PPase domain of Synj1 in DS, AD, and TBC1D24-associated DOORS syndrome." (PMID 33349335, 2020).
Lewy body disease (1 paper, 2025). "Splicing changes observed in the SYNJ1 mutant differentiated hPSCs also overlap with many altered transcript isoforms found in Lewy body disease patient brain samples." (PMID 40950074, 2025).
migraine (1 paper, 2021). "We identified common targets associated with migraine and the hsa‐miR‐155‐5p high confidence target space such as PLP1, TRAK1, SYNJ1, and CREB5." (PMID 34486248, 2021).
prostate carcinoma (1 paper, 2022). A carcinoma that arises from epithelial cells of the prostate gland. "The HPA database suggested that C18orf25, DYNC1LI2, SYNJ1, MAPK1, and ARID4B are highly expressed in normal tissues, and CLOCK, SETD2, ZNF654, XIAP, MIS18BP1, and MBTPS2 are highly expressed in prostate cancer tissues." (PMID 36249009, 2022).
triple-negative breast carcinoma (1 paper, 2025). An invasive breast carcinoma which is negative for expression of estrogen receptor (ER), progesterone receptor (PR), and human epidermal growth factor receptor 2 (HER2). "In triple-negative breast cancer, mechanistic investigations demonstrated that LINC01234 might act as a competing endogenous RNA for miR-429 to upregulate SYNJ1 expression to induce cell proliferation and migration and impair cell apoptosis." (PMID 39991576, 2025).
trisomy 21 (1 paper, 2014). A chromosomal disorder consisting of the presence of an extra chromosome 21. "Although several chromosome 21-encoded products such as APP and synaptojanin 1 (SYNJ1) are thought to contribute to these defects, the detailed molecular mechanisms by which trisomy 21 results in dysfunction of the endocytic trafficking remains largely unclear." (PMID 25152012, 2014).
type 2 diabetes (1 paper, 2019). "Our results show a relative downregulation of SYNJ1 in type 2 diabetes patients on NPWT." (PMID 30221321, 2019).
neurological disorders (5 papers, 2014 to 2025). "Recently, accumulating evidence indicates that mutations and variants of the SYNJ1 gene are linked to many neurological disorders, including early-onset PD and atypical JP, together with ataxia and seizures." (PMID 39273702, 2024). "Missense and nonsense mutations in the 5PPase domain of Synj1 have been associated with several neurological disorders, such as early-onset seizures and early-onset atypical Parkinson’s disease." (PMID 33349335, 2020). "Although patients carrying these mutations display different phenotypes, mutations in SYNJ1 might identify a risk factor for the development of neurological diseases." (PMID 39273702, 2024). "This review will discuss how SYNJ1 operates in pre- and postsynaptic compartments to modulate synaptic activity, as well as its implication in different neurological disorders." (PMID 25302295, 2014). "The critical importance of SYNJ1 at synapses has led multiple teams to investigate its role in neurological disorders such as DS and AD." (PMID 25302295, 2014). "The functions of SYNJ1 in synaptic vesicle recycling and actin dynamics in pre- and postsynaptic compartments are of high interest to understand the physiopathology of PD and, to a larger extent, the role of lipid metabolism in neurological disorders." (PMID 25302295, 2014).
neurodegenerative disease (4 papers, 2017 to 2022). A disorder of the central nervous system characterized by gradual and progressive loss of neural tissue and neurologic function. "The findings in this work shed light on the protein’s binding to phosphatidylinositol 4,5-bisphosphate (PIP2) and give additional insight for future targeting of the protein active site, which might be of interest in neurodegenerative diseases where synaptojanin-1 is overexpressed." (PMID 32419904, 2020).
cancer (2 papers, 2022 to 2025). A tumor composed of atypical neoplastic, often pleomorphic cells that invade other tissues. "Through multi-omics and pan-cancer analyses, CARS2, NFU1, and SYNJ1 were identified as hub genes to construct LRGS and regulate the lactate-related TME in HNSCC." (PMID 39991576, 2025).
infection (2 papers, 2022 to 2024). The state of being infected such as from the introduction of a foreign agent such as serum, vaccine, antigenic substance or organism. "The differentially expressed proteins post-infection include Akap1, Prkaca, Prkab2, Acaca, Acacb, Aka1, Abcf1, Synj1, Braf, Vcl, and Fhod3, which involve insulin receptor signal, glucagon signal pathway, AMPK signal pathway, and Hippo signal pathway." (PMID 35313969, 2022).
tumor (2 papers, 2022). "Moreover, C18orf25, NUP160, DYNC1LI2, SYNJ1, MAPK1, and CLOCK were lowly expressed in tumor tissues." (PMID 36249009, 2022).
bacterial infection (1 paper, 2024). "GFP did not alter its distribution within the cells upon bacterial infection, whereas PLCδ PH-GFP was recruited to S. aureus attachment sites in both control and Synj1-KO cells." (PMID 38358281, 2024).
mental illnesses (1 paper, 2024). "Our findings demonstrate that Synj1 deficiency leads to differential expression of DAT—a major contributor of abnormal DA signaling in DA-related psychiatric disorders." (PMID 39050701, 2024).
movement disorder (1 paper, 2021). Neurological conditions resulting in abnormal voluntary or involuntary movement, which may impact the speed, fluency, quality and ease of movement. "This Movement Disorder Society Genetic mutation database Systematic Review focuses on monogenic atypical parkinsonism with mutations in the ATP13A2, DCTN1, DNAJC6, FBXO7, SYNJ1, and VPS13C genes." (PMID 34396589, 2021).
SYNJ1 also shares sentences with these, for which no sentence is quoted: breast carcinoma (2 papers); Dyskinesia (2); microcephaly (2); Onset (2); amyotrophic lateral sclerosis (1); Athetosis (1); bladder cancer (1); cerebrotendinous xanthomatosis (1); chronic myeloid leukemia (1); cocaine addiction (1); colorectal cancer (1); Crohn disease (1); Dravet syndrome (1); early infantile epileptic encephalopathy (1); episodic ataxia (1); Failure to thrive (1); familial Alzheimer disease (1); focal dystonia (1); glioma (1); glomerulonephritis (1); Hypotonia (1); Hypsarrhythmia (1); IgA nephropathy (1); infantile epileptic encephalopathy (1); Lesch-Nyhan syndrome (1); leukaemia (1); Macrocephaly (1); melanoma (1); mucolipidosis type IV (1); neurofibromatosis type 1 (1).
A further 9 diseases each share a sentence with SYNJ1 in 1 paper.